HLCS (holocarboxylase synthetase)
Description:
Biotin--protein ligase catalyzing the biotinylation of the 4 biotin-dependent carboxylases acetyl-CoA-carboxylase, pyruvate carboxylase, propionyl-CoA carboxylase, and methylcrotonyl-CoA carboxylase.
Synonyms: HCS
Tractability: Small molecule: a high-quality ligand is known; it belongs to a druggable protein family. PROTAC: ubiquitination databases record sites on it; a small molecule that binds it is known.
Target class: Enzyme; Ligase
Gene: Protein-coding gene on chromosome 21 (36,748,626 to 36,990,236, reverse strand). Ensembl gene ENSG00000159267.
Subcellular location: Cytoplasm; Mitochondrion
Subcellular location (Human Protein Atlas): Cytosol
Pathways (Reactome):
Disease: Defective HLCS causes multiple carboxylase deficiency
Metabolism: Biotin transport and metabolism
Gene Ontology:
Molecular function: biotin binding; biotin--[biotin carboxyl-carrier protein] ligase activity; enzyme binding; protein binding; identical protein binding
Biological process: post-translational protein modification; response to biotin; biotin metabolic process
Cellular component: chromatin; cytosol; nuclear lamina; nuclear matrix; cytoplasm; mitochondrion
Genetic constraint (gnomAD): Loss-of-function variants: 48 observed, 69.18 expected, observed/expected ratio (o/e) 0.69, 90% interval 0.55 to 0.88. The upper end of that interval is the gene's LOEUF score, 0.88, which puts it in group 3 of 6, group 1 being the genes least tolerant of losing a copy. Missense variants: 889 observed, 1,015.9 expected, observed/expected ratio (o/e) 0.88, 90% interval 0.83 to 0.93. Synonymous variants: 407 observed, 411.22 expected, observed/expected ratio (o/e) 0.99, 90% interval 0.91 to 1.07.
Gene-disease validity (ClinGen):
ClinGen rates the evidence that HLCS causes each of these diseases.
holocarboxylase synthetase deficiency (autosomal recessive): Definitive. A rare, early-onset and life-threatening, multiple carboxylase deficiency that when left untreated, is characterized by vomiting, tachypnea, irritability, lethargy, exfoliative dermatitis, and seizures that can worsen to coma and death.
Homologues: Orthologues: macaque HLCS (98% identical), chimpanzee HLCS (83% identical), dog HLCS (81% identical), pig HLCS (80% identical), mouse Hlcs (78% identical), rat Hlcs (74% identical), guinea pig HLCS (74% identical), rabbit HLCS (65% identical), tropical clawed frog hlcs (52% identical), Drosophila melanogaster Hcs (27% identical), Caenorhabditis elegans bpl-1 (23% identical), zebrafish hlcs (23% identical).
Diseases named in the same sentence as HLCS in open-access papers:
HLCS is named in the same sentence as 36 diseases in open-access papers, as found by Europe PMC text mining. Sharing a sentence is not in itself a finding about the gene and the disease. The quoted sentences say what the papers report.
multiple carboxylase deficiency (7 papers, 2018 to 2025). "Defects in HLCS lead to dysfunction of all biotin‐dependent carboxylases, a condition known as multiple carboxylase deficiency (MCD)." (PMID 40051682, 2025). "Multiple carboxylase deficiency (MCD) can either be due to biotinidase or holocarboxylase synthetase deficiencies." (PMID 37759536, 2023). "Holocarboxylase synthetase (HLCS) deficiency (OMIM:253,270) is a rare autosomal recessive disorder of biotin metabolism resulting in multiple carboxylase deficiency (MCD)." (PMID 36890565, 2023). "Multiple carboxylase deficiency (MCD, MIM: 253270), a common heritable organic acidaemia, is caused by defects in either biotinidase or holocarboxylase synthetase (HLCS, EC 6.3.4.10)." (PMID 41029453, 2025).
biotinidase deficiency (4 papers, 2018 to 2024). A late-onset form of multiple carboxylase deficiency, an inborn error of biotin metabolism that, if untreated, is characterized by seizures, breathing difficulties, hypotonia, skin rash, alopecia, hearing loss and delayed development. "Biotinidase deficiency has an estimated incidence of 1:60,000, whereas holocarboxylase synthetase deficiency is less frequent." (PMID 34295297, 2021). "Holocarboxylase synthetase deficiency and biotinidase deficiency are autosomal recessive diseases that are associated with multiple carboxylase enzymes deficiencies." (PMID 34295297, 2021).
(HLCS) deficiency (3 papers, 2013 to 2023). "In this paper, we report a Chinese Han pedigree with HLCS deficiency diagnosed by using next-generation sequencing and validated with Sanger sequencing of the HLCS and BTD genes." (PMID 32727382, 2020). "This study aimed to describe the clinical, biochemical, and molecular characteristics of Chinese patients with holocarboxylase synthetase (HLCS) deficiency, and to investigate the mutation spectrum of HCLS deficiency as well as their potential correlation with phenotype." (PMID 36890565, 2023).
breast carcinoma (2 papers, 2014 to 2023). "Elevated expression of HLCS in breast cancer tissues is believed to support biotin carboxylase activities required for oncogenic growth and metastasis." (PMID 38283944, 2023). "We have previously shown that the holocarboxylase synthetase (HLCS) is overexpressed in breast cancer tissue of patients, and silencing of its expression in triple-negative cancer cell line inhibits growth and migration." (PMID 38283944, 2023). "We have previously shown that HLCS is upregulated in breast cancer tissues, and its expression is correlated with lymph node invasion and poor prognosis." (PMID 38283944, 2023). "Although there was no significant change in the expression of PCAF and HLCS, the expression level of GCN5 was reduced, and EHMT-1 was increased in BRCA1-mutated breast cancer (P < 0.05)." (PMID 24675476, 2014). "We have recently shown that suppressing HLCS expression in both low and highly-invasive breast cancer cell lines, MCF-7 and MDA-MB-231, respectively, inhibits their growth and migration, accompanied by cell cycle arrest, indicating the pro-oncogenic role of HLCS." (PMID 38283944, 2023). "We have previously shown that suppression of HLCS expression lowers biotinylation of carboxylases accompanied by impaired growth, migration and invasion, and cell cycle arrest in both luminal subtype (MCF-7) and triple-negative subtype (MDA-MB-231) breast cancer cell lines." (PMID 38283944, 2023).
chronic rhinosinusitis (2 papers, 2017 to 2019). Chronic form of sinusitis. "HLA-DRA has been associated with chronic rhinosinusitis with nasal polyps in previous studies and HLCS, BICD2, VSIR and SLC5A1 may be new targets for future research." (PMID 29253858, 2017). "Comparisons with data from expression quantitative trait loci showed the most skewed allelic distributions in cases with chronic rhinosinusitis with nasal polyps compared with controls for the genes HLCS, HLA-DRA, BICD2, VSIR and SLC5A1." (PMID 29253858, 2017). "Our study indicates that HLCS, HLA-DRA, BICD2, VSIR and SLC5A1 could be involved in the pathogenesis of chronic rhinosinusitis with nasal polyps." (PMID 29253858, 2017). "This study suggests that HLA-DRA as well as four additional genes; HLCS, VSIR, BICD2 and SLC5A1, which have not been previously identified as associated with chronic rhinosinusitis with nasal polyps, could be important for the development of this disease." (PMID 29253858, 2017).
metabolic acidosis (2 papers, 2023 to 2025). "The major clinical manifestations of patients with HLCS deficiency are skin lesions and metabolic acidosis." (PMID 36890565, 2023).
asthma (1 paper, 2017). "HLCS, BICD2, and SLC5A1 have not been connected to asthma, VSIR was implicated with lung function decline in non-asthmatic patients in a genome-wide study published in 2012 but this association could not be confirmed by replication." (PMID 29253858, 2017).
Cholestatic liver disease (1 paper, 2026). "We report the presentation of a Polynesian neonate with severe metabolic acidosis secondary to holocarboxylase synthetase deficiency with the development of cholestatic liver disease thought to be secondary to holocarboxylase synthetase deficiency." (PMID 41383394, 2026). "This is only the second reported case of holocarboxylase synthetase deficiency associated with cholestatic liver disease." (PMID 41383394, 2026).
dermatitis (1 paper, 2025). An inflammatory process affecting the skin. "As was reported, an Italian boy possessed compound heterozygous variations of c.1741G > A and c.1648G > A (p.Val550Met) in the HLCS gene, who presented with an erythematous dermatitis located in the diaper and intertrigenous areas at the age of 5 months." (PMID 41029453, 2025).
glioblastoma (1 paper, 2024). The most malignant astrocytic tumor (WHO grade IV). "Moreover, increased expression of HLCS is correlated with a poor prognosis in glioblastoma, suggesting that targeting biotin-dependent metabolism and the epigenetic pathway might provide a novel therapeutic approach." (PMID 39125325, 2024).
lymph node metastases (1 paper, 2023). "HLCS is a gene important for biotin transport and is predictive of lymph node metastases and poor prognosis in BC." (PMID 36765634, 2023).
short/branched chain acyl-CoA dehydrogenase deficiency (1 paper, 2024). "Five types of organic acid metabolic diseases (short/branched chain acyl-CoA dehydrogenase deficiency (SCADD), methylmalonic cademia (MMA), middle/branched chain acyl-CoA dehydrogenase deficiency (MCADD), holocarboxylase synthetase (HCSD), and glutaric cademia type I (GA-I) were detected." (PMID 38380423, 2024).
trisomy 21 (1 paper, 2024). A chromosomal disorder consisting of the presence of an extra chromosome 21. "By quantifying the ratio of the HLCS gene on chromosome 21 and the fetal-specific rs6636 SNP allele on chromosome 14, they successfully identified 25 out of 28 trisomy 21 cases with no reported FP results." (PMID 38992581, 2024).
cancer (5 papers, 2013 to 2025). A tumor composed of atypical neoplastic, often pleomorphic cells that invade other tissues. "Biotinidase (BTD) and holocarboxylase synthetase (HCS) are the enzymes responsible for biotinylation homeostasis, while deregulation of this process has been associated to various cancers development." (PMID 34948252, 2021). "Of those differentially expressed in our study, 14q32 miRNAs having confirmed targets include miR-127 (located within a CpG island and silenced in many cancers) targeting BCL-6, miR-154 targeting CCND2, miR-433 targeting HDAC6, miR-485-3p targeting NF-YB and miR-539 targeting HLCS." (PMID 23717541, 2013). "As HLCS knockdown cells showed marked reduction of invasion accompanied by reduced MMP1 expression, we checked whether these defective phenotypes were attributed to impaired epithelial-mesenchymal transition program and stemness of cancer cells." (PMID 38283944, 2023).
inborn errors of metabolism (1 paper, 2015). An inherited disorder resulting from an enzyme defect in biochemical and metabolic pathways affecting proteins, fats, carbohydrates metabolism or organelle function. "At two of the six newly identified loci (6q23, ARG1 and 21q22, HLCS), rare variants are known to cause autosomal recessive inborn errors of metabolism, providing a strong biological plausibility for the SNP-metabolite associations." (PMID 26401656, 2015).
HLCS also shares sentences with these, for which no sentence is quoted: glutaric acidemia type I (2 papers); nasal polyps (2); acyl-CoA dehydrogenase deficiency (1); Angelman syndrome (1); argininosuccinic aciduria (1); beta-ketothiolase deficiency (1); biotin deficiency (1); Cerebral folate deficiency (1); Down syndrome (1); Hypertension (1); Intraventricular hemorrhage (1); Methylmalonic aciduria (1); Molybdenum cofactor deficiency (1); pancreatic cancer (1); prostate carcinoma (1); psychiatric diseases (1); Pyruvate carboxylase deficiency (1); Spastic paraplegia 15 (1); tuberculosis (1); tumor (1); X-linked adrenoleukodystrophy (1).